HRAS (HRas proto-oncogene, GTPase)
Diseases named in the same sentence as HRAS in open-access papers (continued):
Sharing a sentence is not in itself a finding about the gene and the disease.
cancer (continued). "The major representatives of the RAS gene family, namely HRAS, KRAS and NRAS, are the most frequently mutated genes in malignant neoplasms, and have been under the spotlight of scientific research for the development of targeted therapies." (PMID 34948093, 2021). "The RAS oncogene family is comprised of three members, KRAS, NRAS, and HRAS, and plays an important role in normal development, but also for cancer development." (PMID 35048068, 2021). "In mice, the deletion of KRAS has been found to be more lethal than the deletion of NRAS and HRAS; therefore, the use of mutant allele-specific inhibitors in humans was proposed to be a more targeted, viable approach for treating RAS mutant cancers." (PMID 34830283, 2021). "HRAS and NRAS mutations are common in other cancer types including head and neck, skin, and hematopoietic cancers." (PMID 33924994, 2021). "The three RAS genes (HRAS, NRAS and KRAS), hereafter collectively referred to as oncogenic RAS, are the most frequently mutated driver proto-oncogenes in cancer, with KRAS being the most prevalent." (PMID 34485382, 2021). "It has been over forty years since the isolation of the first human oncogene (HRAS), a crucial milestone in cancer research made possible through the combined efforts of a few selected research groups at the beginning of the 1980s." (PMID 34062774, 2021). "In fact, some genes, such as HRAS, YOD1, VHL, and CEBPA, were among the most important genes for several cancer types even though their number of mutations in TCGA is very small compared to other genes (ranging from the 4th to 16th percentile)." (PMID 34385450, 2021). "The three isoforms of Ras oncoproteins, HRAS, KRAS, and NRAS, are frequently mutated in a variety of human cancers." (PMID 33580066, 2021). "The incidence of mutated RAS genes differs among human cancers: KRAS is the most highly mutated isoform (85%), followed by NRAS (11%), and HRAS (4%)." (PMID 34466166, 2021). "Of these, the Ras pathway is the most significant pathway, Ras oncogenes are the most common oncogenes in human cancer, members of this superfamily of GTPases (KRAS, NRAS, and HRAS), which encode four highly conserved Ras proteins sharing 85% homology." (PMID 34513708, 2021). "Our findings on the proportion of all cancers with a RAS gene mutation are consistent with a recent analysis that performed a simpler weighted analysis of KRAS, NRAS, and HRAS mutations." (PMID 34645806, 2021). "HotPho successfully identifies likely functional mutational clusters and phosphosites in known cancer proteins, including EGFR, KIT, and KRAS/HRAS/NRAS, many of which are in kinase domains." (PMID 33875650, 2021). "cBioPortal was used to investigate the genomic changes of three Nitroglycerin genes (EGFR, HRAS and MAPK3) associated with respective cancers." (PMID 34764329, 2021). "Similar rebound signaling occurs after MEK inhibitor treatment in HRAS- and NRAS-mutated cancer cells." (PMID 33924994, 2021). "The RAS family of oncogenes (HRAS, NRAS, and KRAS) are among the most frequently mutated protein families in cancers." (PMID 33924994, 2021). "RAS oncogenes (HRAS, NRAS, and KRAS) are one of the most common mutated genes in human cancer with RAS activation occurring in around 30% of all cancers." (PMID 34644109, 2021). "Each harbors overlapping yet distinct sets of co-clustering phosphosites—KRAS p.S89/p.Y96, NRAS p.Y64, and HRAS p.Y32/T35/Y64/Y96—warranting further investigation into their potentially shared and distinct signaling functions across cancer types." (PMID 33875650, 2021). "In terms of cancer-driven mutations, the HRSI group has two significant mutations, including HRAS and KLF5, while the LRSI group has three significant mutations, including ATP6V0A2, BSX, and VNN1." (PMID 34504628, 2021).
cancer (continued). "We therefore sought to better molecularly characterize the mechanisms of resistance to single and combined MEKi and ERKi in oncogenic KRAS-, HRAS- or BRAF-driven cancer cells by focusing analyses on potential rewiring of intracellular signaling cascades." (PMID 33924486, 2021). "RAS genes (HRAS, KRAS, and NRAS) are the most frequently mutated genes in cancer cells, showing a mutation frequency of 30% in all cancer cells." (PMID 34830024, 2021). "RAS isoforms, including HRAS, NRAS and splice variants KRAS4A and KRAS4B, are some of the most frequently mutated proteins in cancer." (PMID 34222339, 2021). "Across a broad range of human cancers, gain-of-function mutations in RAS genes (HRAS, NRAS, and KRAS) lead to constitutive activity of oncoproteins responsible for tumorigenesis and cancer progression." (PMID 34607583, 2021). "Despite the exhibition of a pro-survival role by Ras-mediated autophagy, HRAS-activated autophagy induces caspase-independent cancer cell death." (PMID 33802014, 2021). "Data of the GEO database revealed that HRAS oncogenic signature were enriched in Gins1 high-expressed cancer cells, and silencing GINS1 decreased RAS, SKP2 and LIF expression in our experiments." (PMID 34414190, 2021). "HRAS, NRAS and KRAS, collectively referred to as oncogenic RAS, are the most frequently mutated driver proto-oncogenes in cancer." (PMID 34485382, 2021). "This Ras-isoform dependent propensity to promote stemness strikingly correlates with the mutation frequency of RAS genes, with KRAS, NRAS and HRAS being mutated in 75%, 17% and 7% of RAS-mutant human cancers." (PMID 33544116, 2021). "RAS genes (HRAS, KRAS, and NRAS) comprise the most frequently mutated oncogene family in human cancer." (PMID 34298594, 2021). "In contrast, our integrated genomic-epidemiology approach provides a revised estimate of 15% of cancers harboring a KRAS, NRAS, or HRAS mutation – less than half of those previously reported estimates." (PMID 34645806, 2021). "RAS mutations (HRAS, NRAS, and KRAS) are among the most common oncogenes, and around 19% of patients with cancer harbor RAS mutations." (PMID 34301278, 2021). "In another setting, oncogenic HRAS induced considerable release of sEVs from epithelial cell lines, which were shown to contain the whole cancer cell genome, including the mutant HRAS oncogene." (PMID 34503190, 2021). "Recently, the farnesyltransferase inhibitor tipifarnib has been reintroduced for treatment of HRAS mutant cancers." (PMID 33544116, 2021). "These trials are restricted to HRAS mutant cancers, where the sole prenylation method is via farnesyltransferase, preventing the circumvention of FTIs with different compensatory prenylation methods in other cancers." (PMID 34830283, 2021). "The RAS oncogenes (KRAS, HRAS, and NRAS) are frequently mutated in human cancers, with KRAS being the most commonly affected." (PMID 34947990, 2021). "KRAS and HRAS are two well-known oncoproteins that upregulate autophagy as a pro-survival mechanism for cancer cells to overcome the metabolic stress." (PMID 33802014, 2021). "Mutations affecting members of the RAS family genes (KRAS, HRAS, NRAS) are the most frequent genetic alterations in human cancers accounting for about 27% of all tumors." (PMID 33777798, 2021). "Looking at the top 5 coding mutations, for example, we noted that corresponding genes (FES, TNFSF15, MSRB1, HRAS, and SLC1A7) have all been experimentally implicated in cancer as drivers." (PMID 32859160, 2020). "Mechanistically, pharmacological inhibition of TRPML1 resulted in decreased ERK phosphorylation in HRAS-driven cancers only." (PMID 33322223, 2020).
cancer (continued). "Our data make HRAS a good candidate for modulation by pterostilbene for targeted cancer therapy in combination with conventional chemotherapeutic agents cisplatin plus gemcitabine." (PMID 33036162, 2020). "Three cellular Ras genes encode the four members of the RAS family of small GTPases, KRAS4A, KRAS4B, HRAS, and NRAS, whose mutations drive one-third of human cancers." (PMID 31941155, 2020). "Cancer cells expressing mutant HRAS oncogene exhibit aberrations of chromatin architecture, aneuploidy, cytoplasmic chromatin deposition and formation of micronuclei with a non-random chromosome content." (PMID 32444772, 2020). "The RAS family (KRAS, HRAS, NRAS), are frequently mutated in human cancer, approximately 25% of human malignances harbor RAS mutations." (PMID 32269211, 2020). "Here we show that cancer cells harboring oncogenic HRAS exhibit considerable genetic instability, as indicated by the formation of micronuclei and release of EVs carrying genomic DNA." (PMID 32444772, 2020). "Studies have reported that mitochondrial respiration is upregulated in cancer cells with RB1 deficiency, HRAS mutations, and BCL-2 overexpression." (PMID 33235318, 2020). "HRAS-mutant CCH85 carcinoma cells were sensitive to all three PARP inhibitors as compared to C5N keratinocytes controls with a 10–25 fold change in IC50 for talazoparib which was also corroborated in long-term colony formation assays." (PMID 32398776, 2020). "LIN28 inhibits Let-7 miRNA maturation to promote the expression of Let-7 targets HMGA2, KRAS, MYC22, and HRAS in cancer cells." (PMID 31712708, 2019). "As expected, many apoptosis-related genes, involving ARHGEF2, TNFRSF12A, and SFRP2, were hypermethylated in CMT, and some oncogenes in human cancers, HRAS, FAM83H, and RET, were found as hypomethylated." (PMID 31569550, 2019). "The members of the RAS subfamily of GTPases, which includes KRAS, HRAS, and NRAS, are frequently mutated in cancer." (PMID 31681616, 2019). "The RAS family of proto-oncogenes comprises HRAS, KRAS, and NRAS, which are among the most mutated genes in human cancers." (PMID 31852884, 2019). "RAS subfamily comprises the ubiquitously expressed human RAS proteins KRAS4A, KRAS4B (the two KRAS splice variants), HRAS, and NRAS, which are frequently mutated in cancer." (PMID 31681616, 2019). "RAS genes (NRAS, HRAS, and KRAS) are the most common oncogenes in human cancers with high rates of somatic mutations in pancreatic, lung, and colorectal cancers." (PMID 31835496, 2019). "Of these, KRAS is the most mutated (86% of all RAS-mutant cancers), followed by NRAS (12%), and HRAS (4%)." (PMID 31681587, 2019). "Although oncogenic mutations in the three major Ras isoforms, KRAS, HRAS and NRAS, are present in nearly a third of human cancers, therapeutic targeting of Ras remains a challenge due to its structure and complex regulation." (PMID 31497244, 2019). "Encoded by the KRAS4A, KRAS4B, HRAS, and NRAS genes, RAS family members are among the most frequently altered oncogenes in human cancers." (PMID 31681559, 2019). "We went on to show that genetic or pharmacological inhibition of TRPML1 reduced the proliferation of many different oncogenic HRAS-expressing cancer cell lines via attenuation of the MEK–ERK pathway." (PMID 31526156, 2019). "RAS family genes, including HRAS, KRAS and NRAS, are the most common oncogenes in human cancer, and encode extremely similar proteins made up of chains of 188 to 189 amino acids." (PMID 30971271, 2019). "The protein was found one of the top scored targets of the compound 18, hence, the GTPase HRas protein was found crucial to be targeted for competing cancer." (PMID 30345469, 2018). "In cancer cells, commonly occurring missense mutations in three members of the RAS family genes (HRAS, KRAS and NRAS) result in their constitutive activation." (PMID 29891945, 2018). "Expression levels of PLK1 and HRAS in HCC patients were analyzed using the OncomineTM human cancer microarray database." (PMID 29423069, 2018).
cancer (continued). "These include KRAS, HRAS and NRAS and a variety of different mutations that mirror those found in human cancers with the major RAS effectors such as CRAF, PI3K and RALGDS." (PMID 29989546, 2018). "KRAS, NRAS, and HRAS are the 3 members of the RAS family of GTPases that are the most prevalent oncogenes in cancer progression and have similar cellular functions." (PMID 29568360, 2018). "The three canonical Ras proteins (KRas, NRas, and HRas) are mutated in a broad range of human cancers with KRAS, NRAS, and HRAS mutations accounting for ∼22, ∼8, and ∼3% of all cancers, respectively." (PMID 29282294, 2018). "In this review, aberrant splicing events in cancer-associated genes, namely BCL2L1, FAS, HRAS, CD44, Cyclin D1, CASP2, TMPRSS2-ERG, FGFR2, VEGF, AR and KLF6, will be discussed." (PMID 30463359, 2018). "RAS genes are mutated in different frequencies, KRAS being mutated in 85% of all RAS-driven cancers, NRAS in 12% and HRAS in 3% (COSMIC v82)." (PMID 29455659, 2018). "CUP adenocarcinomas and poorly differentiated carcinomas harboured the highest frequency of variants in genes involved in signal transduction pathways (e.g. MET, EGFR, HRAS, KRAS, and BRAF)." (PMID 29973234, 2018). "Aberrant RAS activation plays causal role in human cancer with an estimated 30% of human tumours harbouring somatic oncogenic mutations mainly in KRAS, but also in NRAS and HRAS." (PMID 28497782, 2017). "By contrast, the methyl donor S-adenosylmethionine has been shown to downregulate the oncogenes c-MYC and HRAS, inhibiting cancer cell growth." (PMID 29125844, 2017). "RAS genes (HRAS, NRAS and KRAS) are the most frequently mutated oncogene family in human cancers, and is strongly associated with cigarette smoking." (PMID 29137294, 2017). "Cancer driver gene mutations (e.g., PIK3CA, HRAS) were identified in only a minority of tumors, and the average mutational load was low at 0.5/MB." (PMID 29084941, 2017). "In 1982-3, orthologs of viral ras oncogenes with point mutations were identified in transforming DNA fragments from human cancer cells both for HRAS and KRAS." (PMID 27102293, 2016). "The RAS genes, KRAS, HRAS, and NRAS, are the most frequently mutated proto-oncogenes in human cancers in the United States and are responsible for 43% of all cancer deaths." (PMID 27684555, 2016). "In particular, activating mutations at codon 61 occur more frequently than at codon 12 of HRAS and NRAS in most cancer types, in contrast to KRAS where a mutation at codon 12 is predominant." (PMID 26799184, 2016). "Therefore, our results also demonstrate that the phenotype in CS and somatic cancers is not only determined by the different transforming potentials of mutant HRAS proteins, but also by the efficiency of exon 2 inclusion resulting from the different HRAS mutations." (PMID 27195699, 2016). "RAS proteins are important regulators of cell fate and up to 30% of all cancers have driving mutations in KRAS, HRAS or NRAS." (PMID 26771141, 2016). "The RAS oncogene, which can exist in either of the HRAS, KRAS, or NRAS isoforms, is found mutated in approximately 30% of all human cancers and produces aggressive, treatment resistant tumors." (PMID 27330862, 2016). "The n1046 mutation is homologous to the HRAS and KRAS mutations that are frequently found in human cancer cells." (PMID 25978500, 2015). "This inhibition of the mTOR pathway translated in blockage of cell growth preferentially in HRAS mutant cancer cell lines." (PMID 26544513, 2015).
cancer (continued). "In particular, activating (“gain-of-function”) mutations in HRAS and KRAS are among the most prevalent tumor initiating mutations found in human cancer cells." (PMID 25978500, 2015). "In this study we were able to show for the first time that HRAS mutant cancer cell lines can be targeted by MEK kinase inhibition." (PMID 26544513, 2015). "Some reports have demonstrated HRAS is not only the oncogene for cancer initiation, but also can increase PCa metastasis." (PMID 26074876, 2015). "Mice deficient in IQGAP were refractory to HRAS-driven carcinogenesis and depletion of IQGAP1 reduced invasion in RAS oncogene-driven cancer cells by suppression of ERK activity." (PMID 26033452, 2015). "When PIK3CA and AKT1 are downstream effectors of RAS, both HRAS and RAC1 are RAS superfamily of small GTPases that cause cancer growth, invasion, and metastasis." (PMID 25356910, 2014). "The receptor tyrosine kinases EGFR and ERBB2, the GTPases KRAS, NRAS, and HRAS, and the kinase BRAF are frequently mutated in cancers and can drive tumor proliferation." (PMID 24874471, 2014). "Despite these differences, there were significant overlaps in the mutational profiles of the two cancer types, including mutations in the NOTCH receptors (NOTCH1-3), HRAS, and PIK3CA that were seen in both HPV-positive and negative disease." (PMID 23663293, 2013). "Although HRAS was historically the most studied RAS gene, it is actually the isoform least mutated in human cancers." (PMID 23202889, 2012). "These genetic changes include CDKN2A deletion and MYC amplification in immortalization, HRAS activation in transformation, PIK3CA activation in the formation of malignant tumors, and RUNX1 deletion associated with poorly-differentiated malignant tumors." (PMID 20169162, 2010). "These events include CDKN2A deletion and MYC amplification in immortalization, HRAS activation in transformation, PIK3CA activation in the formation of malignant tumors, and RUNX1 deletion associated with poorly-differentiated malignant tumors." (PMID 20169162, 2010). "The three RAS oncogenes (HRAS, KRAS and NRAS) are mutationally activated in ~30% of all cancers and are implicated in promoting multiple aspects of the malignant cancer phenotype." (PMID 19682393, 2009). "RAS family proteins, including HRAS, NRAS, and KRAS, are frequently mutated in cancer." (PMID 41986348, 2026). "Interestingly, whilst the spectrum of variants in KRAS/HRAS in human cancer typically involves activating missense variants at codons 12, 13, and 6134, KRAS/HRAS in-frame indels or in-frame duplications have been associated with vascular malformations." (PMID 41350447, 2025). "Consequently, therapeutic strategies targeting HRAS are being pursued in the fields of cancer and RA research." (PMID 39894825, 2025). "Specifically, the Ras family of GTPases is known for regulating actin cytoskeleton dynamics and cell migration, largely through the Ras subfamily of GTPases (HRAS, KRAS, NRAS), which have been found to be mutated in individuals with cancer and drive cancer metastasis." (PMID 41200767, 2025). "Although these HRAS p.G12C and NRAS p.G12C mutations are relatively rare in patients with cancer, these findings suggest that glecirasib could offer new treatment options for these patient populations." (PMID 40304209, 2025). "Notably, Liu's group demonstrated that combining BSO with the NADPH oxidase inhibitor DPI effectively kills cancer cells with HRAS G12V and KRAS mutations, suggesting a promising dual-targeting strategy for RAS-driven cancers." (PMID 40403492, 2025). "Somatic mutations in the KRAS, HRAS, and NRAS genes are often presented in different cancers." (PMID 41438146, 2025). "Studies on the RAS gene family—KRAS, HRAS, and NRAS—have revealed the pivotal role of KRAS mutations in various cancers despite their relatively low frequency in breast cancer, emphasizing the untapped potential for precision treatments targeting this mutation." (PMID 40236954, 2025).